EGFR (epidermal growth factor receptor)
Diseases named in the same sentence as EGFR in open-access papers (continued):
Sharing a sentence is not in itself a finding about the gene and the disease.
diabetic cardiomyopathy (16 papers, 2013 to 2025). Diabetic cardiomyopathy is a disorder of the heart muscle in people with diabetes. "Prior research has established that downregulating EGFR protein expression in myocardial tissue effectively inhibits the onset and advancement of diabetic cardiomyopathy." (PMID 40161384, 2025). "It is known that EGFR activation is a key component in diabetic damage; it involves in insulin sensitivity, and leads to diabetic cardiomyopathy." (PMID 28427241, 2017). "Our findings demonstrate that 11β-HSD1 contributes to the development of diabetic cardiomyopathy through activation of glucocorticoid and EGFR signaling pathway." (PMID 29221204, 2017). "Inhibition of 11β-HSD1 ameliorated structural and functional features of diabetic cardiomyopathy and that this beneficial effect was mediated through modulation of epidermal growth factor receptor phosphorylation." (PMID 29221204, 2017). "As our in vivo studies pointed to an interesting involvement of EGFR in diabetic cardiomyopathy, we investigated whether HG increases EGFR phosphorylation." (PMID 29221204, 2017). "We previously reported that EGFR inhibition attenuates diabetic cardiomyopathy in mice." (PMID 29221204, 2017). "Thus, gefitinib, and other clinically approved EGFR inhibitors that do not exhibit cardiotoxicity, may be considered for the potential treatment of diabetic cardiomyopathy." (PMID 34408653, 2021).
diffuse midline glioma (16 papers, 2021 to 2025). A diffuse glioma that arises from the midline structures of the central nervous system. "Recent studies have documented that in the diffuse midline glioma EGFR mutant, PRC2 inhibition and the consequent H3.3K27me3 loss is related to an epigenetic aberrant overexpression of the EZH2 inhibitory protein EZHIP, instead of to H3F3A variants." (PMID 35456430, 2022). "Other types include infant-type hemispheric glioma, and epidermal growth factor receptor (EGFR) mutant or ACVR mutant—diffuse midline glioma (DMG)." (PMID 38523840, 2024). "The term diffuse midline glioma has now been expanded to incorporate cases with H3.1 or 3.2 mutations and H3-wildtype with EZHIP overexpression and EGFR mutations." (PMID 35693015, 2022). "Our findings highlight the presence of oligodendrocyte precursor cell (OPC)‐like subpopulations, with epidermal growth factor receptor (EGFR)‐expressing OPC‐like cells emerging as a potential tumorigenic origin in diffuse midline gliomas due to their distinct stemness properties." (PMID 41036308, 2025). "Notably, recurrent mutations in EGFR and EZHIP have been implicated in PRC2 inhibition within a specific subgroup now classified under diffuse midline glioma with H3K27-alteration." (PMID 41050069, 2025). "Three tumors (27%) (P2, P5 and P9) are classified in the H3.3K27M mutant sub-type, two (18%) (P10 and P11) in the H3.3G34R/V mutant sub-type, one (9%) (P3) in the IDH mutant sub-type, one (9%) (P6) as a PXA-like pHGG, and one (9%) (P4) as a diffuse midline glioma EGFR mutant." (PMID 35456430, 2022). "Therefore, we diagnosed this case as a diffuse midline glioma EGFR mutant." (PMID 35456430, 2022). "H3K27-altered diffuse midline glioma (DMG) is a fatal disease, including four subtypes H3.3-mutant, H3.1/H3.2-mutant, H3-wildtype with EZHIP overexpression, and EGFR-mutant." (PMID 40849656, 2025).
inflammatory bowel disease (16 papers, 2015 to 2025). A spectrum of small and large bowel inflammatory diseases of unknown etiology. "These proteins were also enriched in extracellular structure organization/extracellular matrix organization/extracellular matrix disassembly, and the major enriched KEGG pathways were related to IL−17 signaling pathway, EGFR tyrosine kinase inhibitor resistance, and inflammatory bowel disease." (PMID 36727076, 2022). "IL-6, which links inflammatory bowel disease (IBD), AGE-RAGE, JAK/STAT, PI3K/Akt, cytokine–cytokine receptor interaction, and EGFR-TKI-resistance signaling pathways, was upregulated by the SYN treatment versus the PL treatment." (PMID 40563358, 2025). "GO and KEGG analyses showed that these targets were highly correlated with EGFR tyrosine kinase inhibitor resistance, PI3K-Akt signaling pathway, JAK-STAT signaling pathway, MAPK signaling pathway, and inflammatory bowel disease (IBD)." (PMID 34221084, 2021).
laryngeal squamous cell carcinoma (16 papers, 1996 to 2025). A squamous cell carcinoma that arises from the larynx. "Overexpression of EGFR was found in laryngeal squamous cell carcinoma and its expression level was significantly associated with HPV infection." (PMID 34429452, 2021). "Marijić demonstrated the inverse expression of mEGFR and nEGFR in squamous cell carcinomas of the larynx and concluded that only one EGFR signaling pathway, membrane or nuclear, controls further carcinogenesis in tumors." (PMID 36982894, 2023). "One study has shown that in patients with laryngeal squamous cell carcinoma, those with low EGFR expression levels have a 5-year OS rate of 81% compared with 25% for patients with high levels of EGFR expression." (PMID 24973959, 2014). "Epidermal growth factor receptor (EGFR) content was determined by a radioligand receptor assay in 140 primary laryngeal squamous cell carcinomas (median value of 8.4 fmol mg-1 protein, range 0-169.9 fmol mg-1 protein)." (PMID 8883413, 1996). "Additionally, patients with laryngeal squamous cell carcinoma had a considerably worse prognosis when their epidermal growth factor receptor expression was increased." (PMID 37373916, 2023). "We present the conceptual study investigated the capacity of minichromosome maintenance-2 (MCM-2), Ki-67, and epidermal growth factor receptor (EGFR) to assess the severity and progression of laryngeal squamous cell carcinoma (LSCC) disease and to study the correlations among these markers." (PMID 34272446, 2021). "A former study in 140 patients with primary laryngeal squamous-cell carcinoma showed that the 5-year survival rate was 81% for patients with EGFR non-expressing tumors, compared with 25% for patients with EGFR-expressing tumors (P < 0.0001)." (PMID 16722544, 2006).
pancreatitis (16 papers, 2016 to 2025). Inflammation of the pancreas. "The impact of AGR2 on EGFR presentation to the cell surface is essential for pancreatitis-associated tissue regeneration in mice." (PMID 33413231, 2021). "The Wnt and EGFR signaling pathways have both been associated with tissue regeneration during pancreatitis." (PMID 27764193, 2016). "Pancreatitis therefore activated EGFR signaling, which was associated with tissue regeneration as represented by cell proliferation." (PMID 27764193, 2016). "This study establishes an essential role for AGR2-induced EGFR signaling in pancreatitis-associated tissue regeneration." (PMID 27764193, 2016). "For instance, a finding using CRISPR-based engineering with higher fidelity discovered that KRAS (G12C) mutants primarily react to covalent-specific G12C inhibitors once EGFR is suppressed, whereas KRAS (G12D) mutants remain susceptible to EGFR inhibition in pancreatic human cancer model." (PMID 40075634, 2025). "Considering that AGR2 was previously associated with tissue regeneration in several lower vertebrates and its importance in EGFR-mediated cell signaling, experiments were conducted to evaluate its role in the murine model of pancreatitis-associated tissue regeneration." (PMID 27764193, 2016). "Thus, consistent with previous work, pancreatitis-associated AGR2 expression initiates EGFR cell signaling, activates YAP1, and induces AREG expression." (PMID 27764193, 2016). "Hyperactivation of EGFR signaling leads to severe pancreatitis, whereas EGFR inhibition improves symptoms and reduces organ damage in AP rats." (PMID 40699778, 2025). "Some studies suggest that hyperactivation of EGFR signaling is related with the induction of pancreatitis." (PMID 40308779, 2025). "Strikingly, the acinar cells in healthy SC pancreata displayed robust activation of EGFR, at levels comparable to those found in SC pancreatitis tissues." (PMID 37643018, 2023). "The murine model that employed caerulein-induced pancreatitis demonstrated the AGR2-induced EGFR signaling, which is necessary for tissue regeneration and the outcome of pancreatitis." (PMID 37175601, 2023). "Our observation that knockout of Muc-1 attenuates NF-κB expression and activation during CVB3-induced pancreatitis leads us to propose that Muc-1 is a signaling effector between EGFR and NF-κB." (PMID 31337812, 2019). "It was shown lately that blockade of EGF/EGFR attenuates pancreatic tumorigenesis induced by KRASG12D or pancreatitis, which supports the essential role of EGF signaling in PDAC." (PMID 28388589, 2017). "The impact of EGFR tyrosine kinase activity on pancreatitis-induced tissue regeneration was evaluated using the EGFR-specific tyrosine kinase inhibitor, AG1478." (PMID 27764193, 2016). "From this perspective, the model clearly demonstrated AGR2's importance for both EGFR signaling and cell proliferation in response to pancreatitis." (PMID 27764193, 2016). "Similar to previous studies, tissue regeneration was initiated in pancreatic acinar cells during pancreatitis, which is also the site of EGFR signaling." (PMID 27764193, 2016). "EGFR signaling during pancreatitis was significantly reduced by AG1478 as determined by cell surface phosphorylated EGFR, nuclear EGR1, and AREG expression." (PMID 27764193, 2016). "The present study therefore establishes for the first time the induction of four molecules, AGR2, EGFR, YAP1, and AREG, each of which have been individually associated with tissue regeneration in other organs, but are now all activated during pancreatitis." (PMID 27764193, 2016). "The impact of AGR2 expression and EGFR signaling on tissue regeneration was evaluated using the caerulein-induced pancreatitis mouse model." (PMID 27764193, 2016). "The results indicate a gene dosage effect between AGR2 and EGFR signaling that affected pancreatitis outcomes." (PMID 27764193, 2016).
pancreatitis (continued). "AGR2 is not expressed in the normal pancreas, but is induced early in the course of pancreatitis, which results in EGFR delivery to the cell surface where signaling is initiated." (PMID 27764193, 2016). "Pancreatitis-induced AGR2 expression enabled EGFR translocation to the plasma membrane, the initiation of cell signaling, and cell proliferation." (PMID 27764193, 2016). "AGR2+/- heterozygotes were therefore able to survive pancreatitis, but exhibited lower levels of EGFR signaling and cell proliferation, and higher levels of serum amylase than wild-type controls." (PMID 27764193, 2016). "Six to 8-week old AGR2+/- heterozygous mice with pancreatitis induced by 1 day of 8 hourly injections displayed cell surface EGFR." (PMID 27764193, 2016). "EGFR inhibition with AG1478 in wild-type mice with pancreatitis still exhibited a significant increase in nuclear YAP1, which was absent in the AGR2-/-null mice." (PMID 27764193, 2016). "The role for EGFR signaling in tissue regeneration in higher vertebrates is less clear, although supportive evidence includes a reduction in pancreatitis-induced tissue damage in rats when EGF was concomitantly administered." (PMID 27764193, 2016). "Notably and recently, D.D.Engle and colleagues found that CA19–9 expression in mice resulted in rapid and severe pancreatitis with hyperactivation of epidermal growth factor receptor (EGFR) signaling." (PMID 33962560, 2021). "The use of histologic criteria, such as the degree of inflammation, to characterize experimental pancreatitis may be misleading in the AGR2-/- null mouse because EGFR signaling is required for the inflammatory response." (PMID 27764193, 2016). "EGFR expression in acinar cells is also induced during pancreatitis." (PMID 27764193, 2016). "AGR2-induced EGFR signaling was essential for tissue regeneration and recovery from pancreatitis." (PMID 27764193, 2016). "Whether AGR2-induced EGFR signaling is essential for tissue regeneration in higher vertebrates was evaluated using a well-characterized murine model for pancreatitis." (PMID 27764193, 2016). "The present study employed the caerulein-induced pancreatitis model to test the hypothesis that AGR2-induced EGFR signaling is necessary for pancreatic tissue regeneration in higher vertebrates." (PMID 27764193, 2016). "Functionally, CA19-9 regulated EGFR hyperactivation by modifying FBLN3 to increase its binding with EGFR, leading to the induction of pancreatitis." (PMID 37209817, 2023). "(E) Immunohistochemistry staining for p-EGFR in iKras* and iKras*;CD11b-DTR pancreata post pancreatitis induction and iKras*;CD11b-DTR pancreata following DT treatment for 3 days and 1 week." (PMID 28980940, 2017). "Although EGFR signaling and cell proliferation, as represented by nuclear EGR1 and MKI67, were significantly induced in AGR2+/- mice with pancreatitis on Day 1, the levels were 65% and 75% lower, respectively, than wild-type AGR2+/+ mice." (PMID 27764193, 2016). "Protein immunoblots of pancreatic homogenates revealed pancreatitis induced AGR2 protein expression and EGFR phosphorylation." (PMID 27764193, 2016). "The present study established that the normal pancreas does not express AGR2, and EGFR signaling is inactive unless pancreatitis is induced." (PMID 27764193, 2016). "Consistent with the absence of AGR2 expression in AGR2-/-null mice, EGFR protein remained in the endoplasmic reticulum during caerulein-induced pancreatitis." (PMID 27764193, 2016). "Consistent with previous work in which AGR2 expression in non-transformed cells resulted in translocation of EGFR to the cell surface and cell signaling, the present study demonstrated that pancreatitis induced AGR2 expression also achieved similar results." (PMID 27764193, 2016).
pancreatitis (continued). "EGFR mRNA expression did not change with the onset of pancreatitis, but EGFR protein translocated from the endoplasmic reticulum to the plasma membrane in acinar cells as indicated by its enhanced co-localization with E-cadherin instead of calreticulin." (PMID 27764193, 2016). "Some studies have not found that EGFR is overexpressed in pancreatitis tissues." (PMID 40308779, 2025). "Importantly, pancreatitis severity and EGFR hyperactivation were attenuated by the treatment of mice with anti–CA19-9 blocking antibodies, including the fully human 5B1 clone, highlighting a glycosylation-based therapeutic vulnerability in pancreatitis and PDA." (PMID 35522218, 2022).
skin reaction (16 papers, 2009 to 2025). "In the present study, we aimed to investigate the association of OS and PFS with anti-EGFR antagonist-induced skin reactions according to age and gender." (PMID 36980549, 2023). "Some retrospective data and randomized trials have shown that the severe skin reactions caused by anti-EGFR antagonists correlate with overall survival (OS) and progression-free survival (PFS), but the result is still controversial." (PMID 36980549, 2023). "This is the most reported organism to cause superinfection in EGFR inhibitor-induced skin reactions." (PMID 34888407, 2022). "Here, we summarize the mechanism of skin toxicity caused by EGFR inhibitors, measures to prevent severe fatal skin toxicity, and provide reference for medical staff how to give care and treatment after adverse skin reactions." (PMID 35223483, 2022). "Compared with BEV, EGFR inhibitors (e.g., cetuximab) appear to be better tolerated in older patients, with a lower incidence of thrombotic events but a higher risk of severe skin reactions." (PMID 40283938, 2025). "Some studies have shown that severe skin reactions caused by anti-EGFR antagonists may be linked to overall survival (OS) and progression-free survival (PFS), but the results are still uncertain." (PMID 36980549, 2023). "However, the currently available anti-EGFR mAbs are associated with a relatively high incidence of AEs including skin reactions and electrolyte disorders." (PMID 33713216, 2021). "Information on the relationship of OS and PFS with anti-EGFR antagonist-induced skin reactions is limited and contentious." (PMID 36980549, 2023). "The occurrence of adverse skin reactions and fatal skin toxicity are the most widespread reasons that limit anti-tumor treatments with EGFR inhibitors." (PMID 35223483, 2022). "Adverse skin reactions are the most common side effects of epidermal growth factor receptor inhibitors (EGFRIs) in the treatment of cancer, significantly affecting the survival rate and quality of life of patients." (PMID 35372072, 2022). "In this paper we reviewed the current available data regarding the clinical significance of skin reaction due to EGFR targeted agents." (PMID 19584908, 2009). "We review the current available data regarding the clinical significance of skin reaction due to EGFR targeted agents and its correlation with response to such therapies." (PMID 19584908, 2009). "About 50–70% of patients using anti-EGFR antagonists will experience skin reactions." (PMID 36980549, 2023). "There are reported cases of superinfection with P aeruginosa in patients with EGFR inhibitor-induced skin reactions, but it is not the most common causative organism." (PMID 34888407, 2022). "Skin reaction is the most common adverse reaction in anti-EGFR treatment." (PMID 32372960, 2020). "Therefore, the topical application of retinoids may be effective in controlling EGFR inhibitor-induced skin reactions." (PMID 24396465, 2014).